AR (androgen receptor)
Diseases named in the same sentence as AR in open-access papers (continued):
Sharing a sentence is not in itself a finding about the gene and the disease.
prostate carcinoma (continued). "A recent study also demonstrated that NSD2 plays a pivotal role in prostate tumorigenesis, where NSD2-mediated H3K36me2 is required for androgen receptor (AR) transactivation through de novo formation of tumor-specific AR enhancers in AR-dependent prostate cancer." (PMID 41301842, 2025). "Androgens are known drivers of prostate cancer, and inhibition of the androgen receptor (AR) signaling axis remains a mainstay of systemic therapy in metastatic hormone-sensitive prostate cancer (mHSPC) and metastatic castration-resistant prostate cancer (mCRPC)." (PMID 39588946, 2025). "For example, mutations in the speckle-type POZ protein (SPOP), a substrate recognition component of the E3 ubiquitin ligase, can disrupt normal AR ubiquitination, leading to increased AR protein stability and enhanced AR signaling, ultimately increasing resistance in prostate cancer cells." (PMID 41079787, 2025). "This interaction disrupts critical protein–protein interactions required for AR transcriptional activity, making EPI-001 effective in both hormone-sensitive and castration-resistant prostate cancer cells, including those expressing AR splice variants lacking the LBD." (PMID 41020902, 2025). "In both androgen-sensitive and castration-resistant AR-driven prostate cancers, AR signaling upregulates the expression of Drp-1, which supports cancer cell survival under various metabolic stresses—such as hypoxia and oxidative stress—thereby enhancing cell survival and proliferation." (PMID 41282600, 2025). "The observed reductions in AR mRNA and protein levels in two PCa cell lines confirm the feasibility and therapeutic relevance of siRNA-LNPs for modulating the AR pathway, which is a key driver of prostate cancer progression." (PMID 40115963, 2025). "As exemplified by the clinical candidates ARV‐110 and ARV‐471, respectively, it has been possible to develop PROTACs against targets previously considered undruggable, including androgen receptor (AR) in prostate cancer and estrogen receptor (ER) in breast cancer, as illustrated in." (PMID 41362117, 2025). "When second-generation AR inhibitors (enzalutamide, dorulatamide) were developed for use in metastatic castrate-resistant prostate cancer, it was speculated that they may prove beneficial in TNBCs expressing AR." (PMID 40003864, 2025). "Niclosamide has already been investigated as an anti-AR-SV therapeutic in prostate cancer." (PMID 40805231, 2025). "The androgen receptor (AR) is a critical driver of prostate cancer (PCa)." (PMID 41193657, 2025). "Growth of benign and malignant prostate tumors is mediated by the androgen receptor (AR)." (PMID 39651632, 2025). "The androgen receptor (AR) nuclear transcription factor pathway is pivotal for prostate cancer development and progression, where the binding of testosterone to the AR activates downstream signalling cascades to regulate cancer cell proliferation, survival, and differentiation." (PMID 39858418, 2024). "As a result, ARLNC1 promotes androgen receptor-dependent prostate cancer cell proliferation." (PMID 38095719, 2024). "In 2001, a distinct effect of PIASy was reported as blocker of AR in prostate cancer." (PMID 38590645, 2024). "Importantly, AHR signaling has been shown to influence several aspects of prostate cancer progression, including AR signaling, cell proliferation, and invasiveness." (PMID 39600743, 2024). "Androgen receptor (AR) is the critical driver of nearly all prostate cancer." (PMID 39489778, 2024). "Some subunits of the Mediator complex are coactivators of the AR in prostate cancer." (PMID 39253786, 2024). "Selective activation of the AT2 receptor has been suggested as therapy for human prostate cancer based on rat studies where the AT2 agonist compound 21 reduced both androgen receptor expression and the proliferative activity of prostate cancer cells in a rat model of disease." (PMID 38763333, 2024).
prostate carcinoma (continued). "Cell thermal shift assays revealedthat 5-H-Y directly binds to AR and acts as an AR antagonist.In contrast, cisplatin, despite forming aggregates with AR, did notshow a proportional inhibitory effect on prostate cancer cell proliferationin accordance with AR expression level." (PMID 39258898, 2024). "Therefore, AR signaling is regarded as one of the most important targets for prostate cancer treatment." (PMID 38474045, 2024). "The AR is a well described and validated drug target in advanced and metastatic prostate cancer although it may play distinct roles in both the stromal and epithelial compartments." (PMID 39088439, 2024). "Enzalutamide is an androgen receptor (AR) inhibitor that works by directly binding to AR on its ligand-binding domain and blocking AR activation and signaling, which is critical for the growth and survival of prostate cancer cells." (PMID 39061175, 2024). "Although therapeutic approaches to develop inhibitors against AR are widely used in the clinic, AR signaling can also be initiated in prostate cancer cells from the bypass via glucocorticoid receptor (GR) signaling, thus making prostate cancer cells resistant to AR inhibitors." (PMID 39655078, 2024). "AR affects a wide variety of cellular activities, including proliferation, apoptosis, migration, invasion, and differentiation, and the expression of AR in prostate cancer is regulated by steroids and peptide hormones." (PMID 39567496, 2024). "The combination of rhythm regulation and AR signal targeting therapy may be an effective means of treating prostate cancer in future." (PMID 39011396, 2024). "Indeed, MYC, MCL-1, and BCL-2 are important oncoproteins in both AR-driven and AR-independent prostate cancer." (PMID 39117800, 2024). "Moreover, we show that Thio-2 which is predicted to bind the BAG domain, suppresses AR activity and other key signaling pathways, to inhibit the growth of prostate cancer cell lines and patient-derived models." (PMID 38412481, 2024). "Prostate cancer growth is often driven by androgen receptor signalling." (PMID 39725830, 2024). "The motif with second highest enrichment (E = 5.1e-89) mapped to the consensus binding site for JUN proteins (E = 2.89e-08), components of the AP-1 transcription activator complex that are known enhance AR activity and stimulate cellular proliferation in prostate cancer cells." (PMID 38745948, 2024). "However, one study showed that low concentrations of BPA stimulated the proliferation of androgen receptor-expressing cells, which inhibited the growth of prostate cancer cells." (PMID 39203725, 2024). "The interaction between AHR and AR signaling pathways provides critical insight into how these molecular mechanisms may contribute to the aggressive nature of prostate cancer in AA men." (PMID 39600743, 2024). "Additionally, its combination with androgen receptor antagonists proved effective in 165 patients with metastatic castration-resistant prostate cancer." (PMID 38339419, 2024). "Interestingly, AR expression in prostate cancer is positively regulated by another histone phosphorylation mark, pY88-H428." (PMID 38965223, 2024). "Menin also promotes AR-positive prostate cancer growth by activating Myc." (PMID 39336822, 2024). "However, the expression of activated MEKK1 induces apoptosis in prostate cancer cells in a manner dependent on the presence of androgen receptor." (PMID 39443331, 2024). "Endocrine therapy for prostate cancer is based on the use of drugs that diminish androgen concentration and androgen receptor (AR) signaling inhibitors and is limited by the functional consequences of AR point mutations and increased expression of constitutively active receptors." (PMID 38104650, 2024). "Although the effects of AR and enzalutamide on ferroptosis in prostate cancer were observed in our study, the relationship between AR, enzalutamide, and ferroptosis remains unclear." (PMID 39097593, 2024).
prostate carcinoma (continued). "The AR was chosen for PROTAC investigation from the outset due to its well-characterized association with androgens and its role in the development and progression of prostate cancer." (PMID 38339414, 2024). "Prostate cancer progression is predominantly driven by AR signaling." (PMID 38702734, 2024). "This review explores the evolution of treatment strategies for metastatic castration-sensitive prostate cancer, emphasizing the benefits of early treatment intensification with androgen deprivation therapy, androgen receptor pathway inhibitors, and chemotherapy." (PMID 39335158, 2024). "AR inhibition remains the mainstay treatment for metastatic prostate cancer, a practice grounded in seminal experiments from 1941, which demonstrated the androgen-driven and androgen-dependent nature of prostate cancer." (PMID 39335158, 2024). "Additionally, androgens involved in normal prostate development and also in prostate cancer act through the androgen receptor (AR)." (PMID 39458961, 2024). "For instance, we have reported that the enzyme CHST11, which is one of several enzymes essential for oncofetal CS synthesis, is regulated by the androgen receptor in prostate cancer, suggesting a direct link between androgen levels and oncofetal CS presentation." (PMID 39406935, 2024). "Through detailed molecular studies of the marine alkaloid manzamine A (MA), we identified transcription factor E2F8 as a previously unknown regulator of AR transcription that prevents AR synthesis in prostate cancer cells." (PMID 38605607, 2024). "Importantly, these results were not limited to AR-negative subtypes but were also observed in AR-positive prostate cancer cells." (PMID 39027480, 2024). "In this review, we discuss the involvement of key TFs, including the E26 Transformation-Specific (ETS) Family (ERG and SPDEF), NF-κB, Activating Protein-1 (AP-1), MYC, and androgen receptor (AR), in prostate cancer while focusing on the molecular mechanisms involved in prostate cancer development." (PMID 38674385, 2024). "Aberrant androgen receptor (AR) signaling has proved to be the driver for prostate cancer (PC)." (PMID 38898995, 2024). "PIAS3 also interacts with AR as co-regulator in prostate cancer." (PMID 38590645, 2024). "Also, the androgen receptor network in prostate cancer [WP2263] was the second (FDR = 1.63 × 10−9) in WikiPathways, and prostate cancer [DOID:10283] ranked sixth (FDR = 6.76 × 10−13) in Disease Ontology." (PMID 39595075, 2024). "We confirmed the expression of LPHNs in all the prostate cancer lines examined, and their levels were considerably higher in AR-positive lines, supporting the claim that LPHNs could represent downstream targets of AR signaling." (PMID 39000396, 2024). "AR play a pivotal role in orchestrating the regulatory mechanisms governing the normal functioning of the prostate, as well as influencing conditions such as benign prostatic hyperplasia and prostate cancer." (PMID 39097593, 2024). "22Rv1 are the most aggressive prostate cancer cell line in vivo that still maintains AR expression." (PMID 38820127, 2024). "In WikiPathways, the top five terms were Malignant pleural mesothelioma [WP5087], Androgen receptor network in prostate cancer [WP2263], Matrix metalloproteinases [WP129], Hepatitis C and hepatocellular carcinoma [WP3646], and Extracellular vesicles in the crosstalk of cardiac cells [WP4300]." (PMID 39595075, 2024). "On standard diagnostic staining, the primary prostate cancer in this case was negative for neuroendocrine markers, but the nodal disease was positive for AR, NKX3.1 and markers of NE differentiation (Synatophysin, and CD56) with a Ki67 index of 60%." (PMID 38374116, 2024). "Additionally, it elicited a strong suppression of tumor growth in xenograft models of prostate cancer and demonstrated a synergistic effect when combined with the AR antagonist enzalutamide." (PMID 38389844, 2024).
prostate carcinoma (continued). "We have found that ERIs also downregulate AR and synergise with enzalutamide in prostate cancer." (PMID 38228924, 2024). "Thus, the androgen biosynthesis pathway and AR signaling are the main therapeutic targets for prostate cancer." (PMID 39146021, 2024). "Because many FDA-approved AR targeting treatments have been established in prostate cancer, these findings suggest a novel targeted treatment strategy in DSRCT could be quickly tested and brought to the clinic." (PMID 38575753, 2024). "The LNCaP cell line is the most widely used AR-positive prostate cancer cell line." (PMID 39061232, 2024). "This validated the concept that blocking the function of the AR could suppress prostate cancer cell growth." (PMID 38339414, 2024). "Enzalutamide is a currently marketed AR antagonist for castration-resistant prostate cancer." (PMID 38339414, 2024). "In prostate cancer, methylation of lysine 9 drives androgen receptor antagonist resistance." (PMID 38758815, 2024). "However, many related literatures indicate that lncRNAs can affect the malignant phenotype of prostate cancer through the AR signaling pathway." (PMID 39655078, 2024). "Osguthorpe and Hagler (2011) observed that bicalutamide could exert a slight partial agonist function in prostate cancer due to its binding site of the AR." (PMID 39063165, 2024). "Additionally, 13 out of 18 AR peaks and 26 out of 32 H3K27ac peaks from RECWAS were located in prostate cancer risk regions listed in the GWAS catalog, compared to 2 out of 8 AR peaks and 5 out of 8 H3K27ac peaks from CWAS." (PMID 39099406, 2024). "Additional specific dependencies may be targetable in these tumors; for instance, since DAB2IP levels show strong inverse correlation with AR activation in CRPC, DAB2IP-deficient prostate cancers may be particularly sensitive to AR inhibitors." (PMID 38902547, 2024). "In the context of prostate cancer, the androgen-repressed gene DECR1 has been implicated in the development of castration-resistant prostate cancer (CRPC) and resistance to androgen receptor (AR)-targeted treatments through regulating polyunsaturated fatty acids (PUFAs) oxidation." (PMID 38195593, 2024). "Moreover, one can envision MBOAT1 as a specific target for the development of therapies in estrogen receptor+ breast cancers and MBOAT2 as the relevant target in androgen receptor+ prostate cancer." (PMID 38908072, 2024). "It has been also suggested that AR inhibition may improve immune checkpoint blockade effectiveness in models of prostate cancer via increased interferon-gamma expression in CD8 + T cells." (PMID 38167882, 2024). "These common and unique structures could also be potential sites for binding of small molecules/RIBOTACs that to reduce the expression of AR that drives prostate cancer progression." (PMID 38554103, 2024). "The execution of growth-suppressive AR transcriptional programs in prostate cancer (PCa) and the potential for reactivation remain unclear." (PMID 39672812, 2024). "The AR has been a therapeutic target in prostate cancer for approximately six decades." (PMID 38339092, 2024). "Moreover, C646 has been found to induce apoptosis in androgen-sensitive castrated prostate cancer cells by interfering with the androgen receptor (AR) and NF-κB pathway." (PMID 39014511, 2024). "Bluemn’s research demonstrates that AR-null prostate cancer is sustained through FGFR signaling." (PMID 38254880, 2024). "As many AR directed therapies are FDA approved for the treatment of prostate cancer, better elucidation of their efficacy and mechanism in DSRCT could lead to quick clinical translation." (PMID 39139449, 2024). "Moreover, in the presence of DHT, UBX‐390 treatment significantly reduced the increased levels of AR signaling‐ and prostate cancer‐related proteins, as compared to ARV‐110 treatment." (PMID 38958553, 2024). "Recently, AR was found to compete with YAP for TEAD occupancy in prostate cancer models." (PMID 39300603, 2024).
prostate carcinoma (continued). "The present study aimed to determine whether LPHNs could serve as downstream effectors of AR and could thereby promote the growth of prostate cancer." (PMID 39000396, 2024). "Additionally, PRMT5 promotes the growth of prostate cancer cells by epigenetically binding to the promoter region of the androgen receptor gene." (PMID 39678513, 2024). "Additionally, the androgen receptor (AR), a steroid hormone receptor and a well-recognized biomarker for predicting prognosis in prostate cancer, is targeted by ALZ003, a curcumin analog." (PMID 39595619, 2024). "Alternative anti-androgen therapy has been widely used as a first-line treatment for castration-resistant prostate cancer, and it may affect treatment outcome of subsequent agents targeting the androgen receptor axis." (PMID 38305451, 2024). "Interestingly, earlier studies have shown that overexpression of Hox genes or NCAM1 is linked with either a NE-like transformation or the development of AR signaling inhibitor-resistant prostate cancer." (PMID 39183332, 2024). "Indeed, it has been shown to inhibit the androgen receptor transcriptional program in both androgen-sensitive and castration-resistant prostate cancer, effectively inhibiting tumor growth in a castration-resistant xenograft model." (PMID 39407454, 2024). "However, genes that are classical AR targets in prostate cancer were not significantly altered by androgen stimulation in melanoma cells, suggesting that the dynamic transcriptional repertoire of AR in melanoma is distinct from that in prostate cancer cells." (PMID 38326303, 2024). "The AR signaling pathway is integral to the development and progression of prostate cancer." (PMID 39184676, 2024). "Darolutamide has been shown to inhibit both wild-type and mutant forms of AR, making it effective against prostate cancer cells that may have developed resistance to other forms of androgen deprivation therapy (ADT)." (PMID 39061232, 2024). "In vivo experiments using an orally active p300/CBP proteolysis targeting chimera (PROTAC) degrader (CBPD-409) showed that p300/CBP degradation potently inhibited tumor growth in preclinical models of castration-resistant prostate cancer and synergized with AR antagonists." (PMID 38586029, 2024). "Interestingly, previous studies have shown that activation of Notch signaling contributes to the development of androgen receptor (AR) independence and resistance to antiandrogens in prostate cancer." (PMID 39137945, 2024). "Furthermore, recent reports indicate that castration-resistant prostate cancer cells exhibit high AR protein stability, thus compromising the efficacy of AR antagonists." (PMID 38339414, 2024). "It is unknown whether AR targeting in the clinic results in downstream biological consequences that are different for AA and EA prostate cancer patients." (PMID 38566104, 2024). "Furthermore, sodium butyrate has been demonstrated in vitro to lower androgen receptor gene expression in prostate cancer cells." (PMID 39840030, 2024). "Drugs capable of simultaneously modulating both AHR and AR signaling pathways could offer a more effective treatment strategy for prostate cancer patients, particularly those with castration-resistant prostate cancer (CRPC), who have limited treatment options." (PMID 39600743, 2024). "Our comparative analysisof the inhibitory effects of the azolato-bridgedcomplexes on the proliferation of AR-positive prostate cancer cellline LNCaP, relative to the established Pt-drug cisplatin, revealednine compounds that demonstrated superior inhibitory effects." (PMID 39258898, 2024). "Furthermore, androgen was also found to induce a nuclear localization of TSPAN8, resulting in the formation of TSPAN8 and an androgen receptor (AR) complex in prostate cancer cells." (PMID 38275818, 2024).